RPL34 (ribosomal protein L34)
Description:
Component of the large ribosomal subunit. The ribosome is a large ribonucleoprotein complex responsible for the synthesis of proteins in the cell.
Synonyms: L34; eL34
Tractability: Small molecule: an approved drug acts on it; a structure with a bound ligand is known; a high-quality ligand is known. PROTAC: UniProt records ubiquitination sites on it; ubiquitination databases record sites on it; its protein half-life has been measured; a small molecule that binds it is known. Other modalities: a drug acting on it is in phase 2 or 3 trials.
Target class: Other cytosolic protein
Gene: Protein-coding gene on chromosome 4 (108,620,508 to 108,632,886, forward strand). Ensembl gene ENSG00000109475.
Subcellular location: Cytoplasm, cytosol; Cytoplasm; Endoplasmic reticulum
Subcellular location (Human Protein Atlas): Cytosol; Endoplasmic reticulum; Nucleoli
Pathways (Reactome):
Metabolism of proteins: Eukaryotic Translation Termination; Formation of a pool of free 40S subunits; GTP hydrolysis and joining of the 60S ribosomal subunit; L13a-mediated translational silencing of Ceruloplasmin expression; PELO:HBS1L and ABCE1 dissociate a ribosome on a non-stop mRNA; Peptide chain elongation; Ribosome Quality Control (RQC) complex extracts and degrades nascent peptide; SRP-dependent cotranslational protein targeting to membrane; ZNF598 and the Ribosome-associated Quality Trigger (RQT) complex dissociate a ribosome stalled on a no-go mRNA
Metabolism of RNA: Major pathway of rRNA processing in the nucleolus and cytosol; Nonsense Mediated Decay (NMD) enhanced by the Exon Junction Complex (EJC); Nonsense Mediated Decay (NMD) independent of the Exon Junction Complex (EJC)
Cellular responses to stimuli: Response of EIF2AK4 (GCN2) to amino acid deficiency
Developmental Biology: Regulation of expression of SLITs and ROBOs
Disease: Viral mRNA Translation
Metabolism: Selenocysteine synthesis
Gene Ontology:
Molecular function: cadherin binding; protein binding; structural constituent of ribosome; RNA binding
Biological process: cytoplasmic translation; negative regulation of myoblast fusion; spermatogenesis; striated muscle contraction; translation
Cellular component: cytosol; cytosolic large ribosomal subunit; cytosolic ribosome; extracellular exosome; cytoplasm; endoplasmic reticulum; ribosome; synapse
Genetic constraint (gnomAD): Loss-of-function variants: 0 observed, 4.18 expected, observed/expected ratio (o/e) 0, 90% interval 0 to 0.72. That is too few expected variants to judge how well the gene tolerates losing a copy. Missense variants: 44 observed, 72.89 expected, observed/expected ratio (o/e) 0.6, 90% interval 0.47 to 0.78. Synonymous variants: 29 observed, 24.83 expected, observed/expected ratio (o/e) 1.17, 90% interval 0.87 to 1.59.
Homologues: Orthologues: chimpanzee RPL34 (100% identical), dog RPL34 (100% identical), guinea pig RPL34 (100% identical), macaque RPL34 (100% identical), pig RPL34 (100% identical), rabbit RPL34 (100% identical), mouse Rpl34 (99% identical), rat Rpl34l1 (98% identical), tropical clawed frog rpl34 (98% identical), zebrafish rpl34 (94% identical).
Diseases named in the same sentence as RPL34 in open-access papers:
RPL34 is named in the same sentence as 26 diseases in open-access papers, as found by Europe PMC text mining. Sharing a sentence is not in itself a finding about the gene and the disease. The quoted sentences say what the papers report.
non-small cell lung carcinoma (7 papers, 2016 to 2022). A group of at least three distinct histological types of lung cancer, including non-small cell squamous cell carcinoma, adenocarcinoma, and large cell carcinoma. "Increased expression of RPL34 has been shown to be involved in malignancy progression in gastric cancer, osteosarcoma, non-small cell lung cancer, esophageal cancer, and glioma." (PMID 36293493, 2022). "Overexpression of Rpl34 promotes cell proliferation and is involved in many types of cancer, including human non-small cell lung cancer, gastric cancer, and pancreatic cancer." (PMID 30596102, 2018). "RPL34 regulates cell cycle transition by inhibiting Cdk4 and Cdk5 in HeLa cells, and over-expression of RPL34 promotes cell proliferation in human non-small cell lung cancer and gastric cancer." (PMID 27845896, 2016). "Alteration in RPL34 expression affects non-small cell lung cancer cell proliferation." (PMID 34795329, 2021). "In addition, overexpression of RPL34 is suggested to promote malignant proliferation of non-small cell lung cancer (NSCLC)." (PMID 31576243, 2019). "Similarly, RPL34 is up-regulated in non-small cell lung carcinoma (NSCLC) tissues when compared with normal ones." (PMID 34873618, 2021).
pancreatic cancer (6 papers, 2016 to 2024). "To assess the effect of RPL34 on pancreatic tumor metastasis in vivo, we generated lung metastasis SCID mice models with PANC-1-luc-NC and PANC-1-luc-KD cells." (PMID 27845896, 2016). "However, the expression status and function of RPL34 in pancreatic cancer (PC) remains unclear." (PMID 27845896, 2016). "Knockdown of RPL34 is also shown to have a negative effect on pancreatic cancer cells by inhibiting tumor proliferation, metastasis and promoting apoptosis." (PMID 34873618, 2021).
esophageal cancer (4 papers, 2019 to 2022). A primary or metastatic malignant neoplasm involving the esophagus. "Ribosomal Protein L34 (RPL34) functions as an oncogene and modulates esophageal cancer cells by the inactivation of the PI3K/Akt signaling pathway, and silencing of RPL34 inhibits the proliferation and metastasis of esophageal cancer cells." (PMID 33435549, 2021). "Interestingly, RPL5 is determined to act tumor suppressive in various cancer types, also melanoma and RPL34 seems to be tumour suppressive in esophageal cancer." (PMID 35883595, 2022). "Down-regulation of ribosomal protein L34 (RPL34) could hamper the multiplication of esophageal cancer cells." (PMID 30857280, 2019).
gastric cancer (4 papers, 2016 to 2022). A primary or metastatic malignant neoplasm involving the stomach. "Recently, two reports revealed RPL34 promoted cell proliferation in non-small cell lung and gastric cancers; however, the roles for RPL34 in cell malignances and the mechanisms of its dysregulation remain unexplored in PCs." (PMID 27845896, 2016).
osteosarcoma (4 papers, 2016 to 2022). A usually aggressive malignant bone-forming mesenchymal neoplasm, predominantly affecting adolescents and young adults. "RPL34 upregulation is indicative of undesirable clinical outcomes in osteosarcoma as well as silencing RPL34 weakens osteosarcoma proliferation." (PMID 35836470, 2022). "For example, the expression of RPL34 was found to be more highly in osteosarcoma tissues compared with normal adjacent tissue and was correlated with a poor prognosis." (PMID 34993140, 2021). "Survival analysis showed that high expression of RPL34 predicted a poor prognosis for osteosarcoma patients." (PMID 27883047, 2016). "In this study, real-time quantitative PCR (RT-qPCR) and immunohistochemistry revealed that RPL34 was highly expressed in osteosarcoma tissues when compared to adjacent tissues and normal bone tissues." (PMID 27883047, 2016). "Our findings suggest that RPL34 plays an important role in the proliferation of osteosarcoma cells." (PMID 27883047, 2016). "Ribosomal protein L34 (RPL34) has been increasingly recognized to promote the proliferation of malignant cells, but its role in osteosarcoma has not been investigated." (PMID 27883047, 2016).
glioma (3 papers, 2022 to 2025). A benign or malignant brain and spinal cord tumor that arises from glial cells (astrocytes, oligodendrocytes, ependymal cells). "Ribosomal protein L34 (RPL34) knockdown represses glioma cells’ growth and migration via inhibiting the JAK/STAT3 pathway." (PMID 40321161, 2025).
leukemia (2 papers, 2014 to 2026). A malignant (clonal) hematologic disorder, involving hematopoietic stem cells and characterized by the presence of primitive or atypical myeloid or lymphoid cells in the bone marrow and the blood. "Ribosomal Protein L34 (RPL34), a leukemia-associated protein, is located head to head with RP11-462C24.1." (PMID 24908062, 2014).
colon cancer (1 paper, 2014). "RPL34 was also shown highly expressed in the colon cancer line RKO (a human colon cancer line)." (PMID 24908062, 2014).
glioblastoma (1 paper, 2023). The most malignant astrocytic tumor (WHO grade IV). "For example, with glioblastoma, eS6 (RPS6), eS27 (RPS27), uS8 (RPS15A) and eL34 (RPL34) are known as oncogenic, whereas uL18 (RPL5), uS17 (RPS11), uS9 (RPS16) and uS13 (RPS18) are found to have a tumor-suppressive function." (PMID 37511213, 2023).
ischemic stroke (1 paper, 2023). A stroke disorder caused by obstruction of blood flow to the brain, due to thrombotic (local blood clot formation) or embolic (due to a blood clot or other material traveling from another site) event. "The possibility of Rpl34 as a novel prognostic biomarker and therapeutic target for ischemic stroke was also reported previously." (PMID 36975497, 2023).
oral squamous cell carcinoma (1 paper, 2020). "FMNL2 regulates the invasiveness of cancer cells by driving β1-integrin internalization and RPL34 could promote cell growth and metastasis of oral squamous cell carcinoma." (PMID 32127786, 2020).
rheumatoid arthritis (1 paper, 2019). A chronic, systemic autoimmune disorder characterized by inflammation in the synovial membranes and articular surfaces. "Thus, the identified mediated trans-eQTLs not only suggest a biological mechanism for the trans-association of rs2239804 and RPL34, but also suggest a role of the mediated pathway in the disease etiology of ulcerative colitis and rheumatoid arthritis." (PMID 30925861, 2019).
cancer (15 papers, 2016 to 2026). A tumor composed of atypical neoplastic, often pleomorphic cells that invade other tissues. "RPL34 is another ribosomal protein that has been implicated in several cancer types." (PMID 37190091, 2023). "In here, we mention some examples including RPL34 that is up-regulated in esophageal cancer and its KD inhibits cancer cell proliferation, migration and invasion in vitro by down-regulating the protein expression level of p-PI3K and p-Akt." (PMID 34873618, 2021). "HPF1, RPL34, and EXOSC9 were the most common genes present in FRG1 associated pathways across the cancer types." (PMID 34795329, 2021). "In general, RPL34 and some other RPs are thought to promote development and progress of cancer cells by regulation of the mitogen-activated protein kinase (MAPK) increasing their proliferation and as well as their resistance to apoptosis." (PMID 30105457, 2018). "ENSG00000109475, RPL34, has also been predicted to be a candidate gene to distinguish between the six cancer subtypes and healthy control." (PMID 29152097, 2017). "From all RPs, RPL34 seems to be deregulated most frequently in many types of human cancers." (PMID 30105457, 2018). "RPL34 expression is significantly upregulated in tumor cells compared to adjacent healthy tissues, and over-expression of RPL34 may promote the abnormal proliferation of cancer cells." (PMID 36160439, 2022). "Knockdown of RPL34 by a lentivirus-mediated shRNA in NSCLC cell line H1299 is correlated to a significant decrease in cancer cell proliferation and increase in apoptosis and S-phase arrest, suggesting that RPL34 may play an important role in the development of NSCLC." (PMID 34873618, 2021). "From the top 20 genes correlated with FRG1 across cancer types, we found that three genes (HPF1, RPL34, and EXOSC9) were common." (PMID 34795329, 2021).
tumor (10 papers, 2016 to 2024). "Clinically, our data indicate a positive association of RPL34 expression with tumor stage and metastasis in PCs." (PMID 27845896, 2016). "High tumour staining for each of HMGA2, MUC5AC/6, IDH1, PIWIL2, DNA index, and RPL34 was significantly associated with poorer OS upon multivariable analysis." (PMID 38398089, 2024). "Here, RPL34 promotes cell proliferation, colony formation, migration, invasion, and drug resistance of PC, whereas siRNA-mediated RPL34 knockdown reduces these processes and, consequently, decreases PC tumor growth and metastasis which is accompanied by the induction of apoptosis." (PMID 30105457, 2018). "In vivo assays demonstrate that RPL34 silencing inhibits PC tumor growth and metastasis." (PMID 27845896, 2016). "Taken together, these data demonstrate that RPL34 silencing could effectively reduce tumor growth and metastasis of PC in vivo." (PMID 27845896, 2016). "Knockdown of RPL34 sensitized the tumor cells to gemcitabine and 5-Fu." (PMID 27845896, 2016). "In this study, we found that RPL34 expression was upregulated in PC tissues and positively correlated with pAJCC stage, lymphatic metastasis and angiolymphatic invasion in PC patients, which indicates RPL34 might play a crucial role in tumor development of PCs." (PMID 27845896, 2016). "We infer that HIVEP3, by collaborating with the ribosomal protein (RP) family, such as RPL15, RPL34, and RPS24, could regulate tumor cell cycle and apoptosis and promote tumor proliferation and infiltration metastasis, angiogenesis, or other malignant biological behaviors." (PMID 35535739, 2022).
infection (2 papers, 2019 to 2020). The state of being infected such as from the introduction of a foreign agent such as serum, vaccine, antigenic substance or organism. "In addition, RNA interference of ribosomal protein RPL34 causes serious damages to abortive infection of Autographa californica multiple nucleopolyhedrovirus, indicating that ribosomal components are essential for productive baculovirus infection." (PMID 32420802, 2020).
RPL34 also shares sentences with these, for which no sentence is quoted: breast carcinoma (2 papers); anemia (1); chronic myeloid leukemia (1); depression (1); lymph node metastasis (1); melanoma (1); myocardial infarction (1); Pancytopenia (1); schizophrenia (1); Stroke (1); ulcerative colitis (1).